IPMK (inositol polyphosphate multikinase)
Diseases named in the same sentence as IPMK in open-access papers (continued):
Sharing a sentence is not in itself a finding about the gene and the disease.
Glucose intolerance (1 paper, 2025). Glucose intolerance (GI) can be defined as dysglycemia that comprises both prediabetes and diabetes. "Here, we report that the loss of skeletal muscle IPMK (henceforth referred to as MKO) disrupts insulin sensitivity and lipid utilization, leading to increased body weight, glucose intolerance, and reduced exercise tolerance." (PMID 40141045, 2025).
Hepatic steatosis (1 paper, 2024). Steatosis is a term used to denote lipid accumulation within hepatocytes. "Hepatic IPMK deficiency worsened hepatic steatosis, elevated serum ALT and AST levels, and expression of inflammatory genes in mice fed MCDD, suggesting a role as a molecular mediator in the effect of TRF in NASH." (PMID 38338668, 2024). "Our results demonstrate that TRF attenuates MCDD-induced NASH via IPMK-mediated changes in hepatic steatosis and inflammation." (PMID 38338668, 2024).
muscular disease (1 paper, 2016). Myopathy is a peripheral nervous system disease consisting of any abnormal condition or disease of the muscular tissues; commonly designates a disorder involving skeletal muscle. "Until now, studies about the role of IPMK in skeletal muscle differentiation or muscular diseases were lacking." (PMID 27563828, 2016).
post-traumatic stress disorder (1 paper, 2019). An anxiety disorder precipitated by an experience of intense fear or horror while exposed to a traumatic (especially life-threatening) event. "Our discovery that IPMK fine-tunes Syt2 expression in the forebrain highlights the importance of fully establishing neural functions of IPMK and offers insights into the treatment and management of psychiatric diseases such as post-traumatic stress disorder." (PMID 31221192, 2019).
Salmonella Infections (1 paper, 2013). Infections with bacteria of the genus SALMONELLA. "In IPMK knockout embryonic stem (ES) cells, we observed a significant decrease in Akt activation upon Salmonella infection, compared to wild type control cells." (PMID 23990921, 2013). "We report that Class II PI3-kinase beta isoform, IPMK and other kinases identified from a kinase screen all contribute to Akt activation during Salmonella infection." (PMID 23990921, 2013).
Sepsis (1 paper, 2023). Sepsis is defined as life-threatening organ dysfunction caused by a dysregulated host response to infection. "As revealed from our previous report, genetic deletion of myeloid IPMK in mice was shown to protect host from sepsis as well as LPS-stimulated inflammation." (PMID 36830701, 2023). "Consequently, conditional deletion of IPMK in myeloid cells protects mice against polymicrobial sepsis and lipopolysaccharide-induced systemic inflammation." (PMID 36830701, 2023). "Since the main signaling action of macrophage IPMK appears to rely on its non-catalytic role in controlling TRAF6, developing ways to selectively deplete macrophage IPMK levels could be useful to manage uncontrolled inflammatory response, such as sepsis." (PMID 36830701, 2023).
small-intestine neuroendocrine tumors (1 paper, 2025). "The discovery of genetic alterations in the IPMK gene in familial small-intestine neuroendocrine tumors (SI-NETs) has provided insights into IPMK’s potential role in the pathogenesis of these rare cancers." (PMID 41008573, 2025). "Engineering SI-NET–specific IPMK mutations in mice would be an effective approach to clarify the role of IPMK in the development and progression of small intestinal neuroendocrine tumors (SI-NET)." (PMID 41008573, 2025).
triple-negative breast carcinoma (1 paper, 2024). An invasive breast carcinoma which is negative for expression of estrogen receptor (ER), progesterone receptor (PR), and human epidermal growth factor receptor 2 (HER2). "We found that the protein expression levels of PIPKIα and IPMK did not correlate with ER-positive, PR-positive, HER2-positve, or triple-negative breast cancer." (PMID 38565949, 2024).
cancer (10 papers, 2019 to 2025). A tumor composed of atypical neoplastic, often pleomorphic cells that invade other tissues. "Key areas of investigation should include the role of IPMK in cancer metastasis and wound healing, potentially opening new avenues for therapeutic interventions." (PMID 41008573, 2025). "Given the immune system’s complexity and its central role in both tissue inflammation and cancer therapies, understanding how IPMK regulates immune cell activation within diverse tissue contexts is critical for clarifying disease mechanisms." (PMID 41008573, 2025). "Inositol polyphosphate multikinase (IPMK) is a kinaselinked toseveral cancers; recent development of a large panel of ATP-competitiveinhibitors has reinvigorated enthusiasm for targeting IPMK." (PMID 41237254, 2025). "A study in epithelial ovarian cancer suggested that IPMK is one of the targets of miR-18a, thereby mediating cancer cell growth." (PMID 36830701, 2023). "Additionally, future directions should focus on clarifying IPMK’s contribution to cancer cell proliferation, particularly in tumors with aberrant AKT activation." (PMID 41008573, 2025). "Since genes involved in development are often dysregulated in cancer, uncovering these mechanisms could also provide insights into the largely unknown role of IPMK in tumorigenesis." (PMID 41008573, 2025). "Also, our discovery demonstrates that PIPKIα and IPMK are novel therapeutic targets to disrupt the YAP/TAZ–TEAD pathway in cancer." (PMID 38565949, 2024). "PIPKIα overexpression is reported in breast and other cancer types, while the implications of IPMK in cancer are largely unknown." (PMID 38565949, 2024). "The precise relationship between IPMK and the activation of the SWI/SNF complex in cancer and other diseases remains to be elucidated." (PMID 41008573, 2025). "The function of 6 NRGs in our signature, including FASLG, IPMK, FLT3, SLC39A7, HSP90AA1, and LEF1, are studied in various cancer types, including BC." (PMID 35864548, 2022).
infection (8 papers, 2019 to 2024). The state of being infected such as from the introduction of a foreign agent such as serum, vaccine, antigenic substance or organism. "This virus exhibits the same profile as the virus produced in WT cells: a modest but highly reproducible reduction in infections in the KO cells, particularly the IPMK-KO cells." (PMID 38464197, 2024). "On the other hand, infection of IPMK-KO or IPPK-KO target cells with normal MLV was somewhat less efficient than infection of controls; this is clearly contrary to results with HIV-1 5,25, which we confirmed as part of our study." (PMID 38464197, 2024). "We found a highly reproducible reduction in infections in the KO cells, with a larger decrease in IPMK-KO than in IPPK-KO cells." (PMID 38464197, 2024). "As previously shown, complementation of IPMK partially rescued the >2-fold defect in HIV-1CA WT infection observed in IPMK KOVector cells (black bars)." (PMID 34613803, 2021). "We generated twelve IPMK-deficient MT4 target cell clones and six control clones and performed single cycle infection assays using HIV-1WT and HIV-1K359A/T371I." (PMID 34454514, 2021). "Infection of the CEM IPMK KO clones or WT cells with HIV-1VSVg confirmed these results." (PMID 33476323, 2021). "HIV-1 spread remained delayed in all IPPK and IPMK KO clones tested even when the inoculum the was increased by 10- or 180- fold, confirming that the defect in spread was minimally dependent on multiplicity of infection (MOI)." (PMID 33476323, 2021). "In agreement with previous studies, we found that IPMK KO target MT4 cells were fully susceptible to infection by HIV-1WT, indicating that IP6 from target cells is not required to initiate a productive cycle of infection." (PMID 34454514, 2021). "Thus, the reduced infection previously observed using viral supernatant produced in IPPK-deficient cells was probably the result of a reduction in production rather than the ability of virions to infect, as demonstrated here for both IPPK and IPMK." (PMID 31851928, 2019). "By contrast, in CEM cells, we observed that HIV-1 single cycle infection was typically decreased in most IPPK KO and IPMK KO clones, with IPMK KO being more deleterious to single cycle infection." (PMID 33476323, 2021). "To further confirm that the reduced infection of the KO cells resulted from the lack of the IPMK and IPPK, we tested whether transient transfection with expression vectors for the missing enzymes could reverse the effect." (PMID 38464197, 2024). "We found that this treatment reduced infection of the IPPK-KO cells, while we could not detect an effect in the control cells or the IPMK-KO cells." (PMID 38464197, 2024).
tumor (7 papers, 2018 to 2024). "In vitro assay was performed to evaluate the role of selected gene inositol polyphosphate multikinase (IPMK) in BC progression and tumor immunity." (PMID 35864548, 2022). "It was discovered that IPMK expression was lower in PTC tumor tissues than in normal tissues, but that high expression was linked with a poor prognosis in PTC." (PMID 36186479, 2022). "In contrast, tumor samples had lower levels of IPMK (p = 0.0010), SPATA2 (p = 0.0071), and KLF9 (p = 0.0002)." (PMID 36186479, 2022). "Although the correlation between IPMK and tumor immunity has been preliminarily proved in our study, further research is needed to explore how IPMK regulates the immune microenvironment of BC." (PMID 35864548, 2022). "IPMK was found to promote BC progression and regulate tumor immunity." (PMID 35864548, 2022). "Finally, to further determine the role of IPMK and the AMPK/ULK1 pathway in ebastine-mediated antitumor activity in vivo, we examined expression of IPMK and the AMPK/ULK1 pathway in subcutaneous tumor tissues." (PMID 36632464, 2023). "The role of IPMK in tumor immunity has not been studied previously." (PMID 35864548, 2022).
inflammation (1 paper, 2024). Aberrant reaction of the microcirculation characterized by movement of fluid and leukocytes from the blood into extravascular tissues. "Additionally, IPMK has been associated with liver inflammation and oxidative stress." (PMID 38338668, 2024).
IPMK also shares sentences with these, for which no sentence is quoted: Obesity (2 papers); psoriasis (2); rheumatoid arthritis (2); anorexia nervosa (1); autistic disorders (1); bulimia (1); colorectal cancer (1); eating disorder (1); intestinal diseases (1); intestinal tumors (1); liver inflammation (1); lupus nephritis (1); malaria (1); Onset (1); osteoporosis (1); ovarian cancer (1); ovarian tumor (1); polycystic kidney disease (1); psychiatric diseases (1); small intestinal carcinoids (1); type 2 diabetes (1); ulcerative colitis (1).